PXDN (peroxidasin)
Diseases named in the same sentence as PXDN in open-access papers (continued):
Sharing a sentence is not in itself a finding about the gene and the disease.
glaucoma (9 papers, 2014 to 2025). Increased pressure in the eyeball due to obstruction of the outflow of aqueous humor. "PXDN, a tier 3 target gene with tier 3A evidence for druggability, was the only putative target gene associated with increased glaucoma risk." (PMID 40635100, 2025). "Biallelic PXDN variants have been reported with various eye anomalies including microphthalmia, congenital cataracts, microcornea, sclerocornea, and glaucoma." (PMID 32224865, 2020). "PXDN mutations lead to severe eye disorders, including microphthalmia, cataract, glaucoma, and anterior segment dysgenesis in humans and mice." (PMID 31817535, 2019). "Homozygous mutation in PXDN causes developmental defects including congenital cataract, corneal opacity and glaucoma, abnormalities which are also present in PXDN mutant mice." (PMID 29775486, 2018). "Noteworthy is that certain PXDN variants have been associated with a congenital form of glaucoma." (PMID 36421707, 2022). "Our studies also provide insights for the eye defects found in the patients with PXDN mutations, which could aid in the development of novel strategies to treat congenital anterior segment dysgenesis including corneal opacity, cataract and glaucoma." (PMID 24895407, 2014). "Taking aniridia as an example, whilst PAX6 mutations remain the predominant cause, variants in CYP1B1, FOXC1, PXDN and SOX11 have also been reported in patients with childhood glaucoma and aniridia." (PMID 41011222, 2025). "Moreover, the PXDN mutants exhibited an early-onset glaucoma and progressive retinal dysgenesis." (PMID 27409795, 2016). "By using a comprehensive analysis pipeline, we identified five potential therapeutic targets for glaucoma: two tier 1 genes (CPXM1 and FLT4), one tier 2 gene (INSR), and two tier 3 genes (CPZ and PXDN)." (PMID 40635100, 2025).
glioblastoma (9 papers, 2016 to 2025). The most malignant astrocytic tumor (WHO grade IV). "In U87.MGΔEGFR glioblastoma cells with constitutive expression of Epidermal growth factor receptor (EGFR) — a known regulator of PI3K/Akt signalling — PXDN was the most highly up-regulated gene." (PMID 37801286, 2023). "Consistent with our previous findings, the expressions of NUP107, DRAM1, RNF19A, PXDN, HEY2, F2R, and BMP2 were up-regulated in gliomas (glioblastoma multiforme + lower grade glioma)." (PMID 36245971, 2022). "TOP2A, COL4A1 and PXDN were significantly upregulated and ANK3, ARRB1 and ANO4 markedly downregulated in glioblastoma compared to controls." (PMID 32962742, 2020). "However, the effects of PXDN in prognostic performance and clinical implications in glioblastoma multiforme (GBM) remains unknown." (PMID 36118855, 2022).
prostate carcinoma (8 papers, 2019 to 2023). A carcinoma that arises from epithelial cells of the prostate gland. "Peroxidasin (PXDN) encodes a heme-containing peroxidase that is involved in extracellular matrix formation associated with prostate cancer." (PMID 36245971, 2022). "Further studies of its clinically relevant traits subsequently determined that a high PXDN expression is often accompanied by a higher stage in prostate cancer, and this could be one of the reasons associated with a poor prostate cancer prognosis." (PMID 35982948, 2022). "Therefore, PXDN may be a biomarker associated with prostate cancer and a potential therapeutic target." (PMID 31234468, 2019). "The Nrf2-mediated oxidative response pathway was also among the most differentially regulated between PXDN knockdown and controls in C4-2 prostate cancer cells." (PMID 37801286, 2023). "In prostate cancer, however, the opposite trend was observed, with PXDN depletion in C4-2 cancer cells resulting in an increase in cellular ROS." (PMID 37801286, 2023). "Short hairpin RNA (shRNA) depletion of PXDN in C4-2 prostate cancer cells also reduced cell viability and colony forming ability in soft agar." (PMID 37801286, 2023). "In contrast, in a panel of prostate cancer cell lines, PXDN protein levels were found to be higher in cells expressing Snai1 and vimentin." (PMID 37801286, 2023). "Recent reports suggest that peroxidasin (PXDN) promotes tumorigenesis and the survival of prostate cancer cells by inhibiting oxidative stress through the removal of ROS and inducing apoptosis through the Warburg effect." (PMID 35330413, 2022). "A recent report suggests that PXDN promotes prostate cancer cell tumorigenicity and viability by eliminating ROS to suppress oxidative stress and apoptosis via the Warburg effect." (PMID 32751434, 2020). "We have previously discovered an upregulation in PXDN mRNA when Snail transcription factor was overexpressed in prostate cancer cells." (PMID 31234468, 2019). "Overall, the data suggest that PXDN promotes progression of prostate cancer by regulating the metabolome, more specifically, by inhibiting oxidative stress leading to decreased apoptosis." (PMID 31234468, 2019). "We wanted to analyze what role PXDN plays in regulating Reactive Oxygen Species (ROS) in prostate cancer." (PMID 31234468, 2019). "In this study, we found that PXDN expression increases with prostate cancer progression, and that knockdown of PXDN leads to increased apoptosis possibly via upregulation of H2O2 in prostate cancer cells." (PMID 31234468, 2019). "We analyzed PXDN expression in prostate tissue by immunohistochemistry and found increased PXDN expression with prostate cancer progression as compared to normal tissue or cells." (PMID 31234468, 2019). "Collectively we conclude that PXDN promotes prostate cancer progression by scavenging ROS to possibly inhibit oxidative stress and apoptosis." (PMID 31234468, 2019). "Additionally, in ARCaP prostate cancer cells transfected with Snai1 cDNA to overexpress Snai1, PXDN expression was significantly fold up-regulated compared with control." (PMID 37801286, 2023). "High expression of PXDN has been confirmed in prostate cancer cells overexpressing Snail." (PMID 32751434, 2020). "Proteomic profiling was performed to investigate global pathways that may be regulated by PXDN in prostate cancer." (PMID 31234468, 2019). "We hypothesized that PXDN promotes prostate cancer progression via regulation of metabolic and oxidative stress pathways." (PMID 31234468, 2019). "We speculated that increased PXDN in prostate cancer may still scavenge ROS to prevent deleterious overproduction." (PMID 31234468, 2019). "We propose that PXDN plays a role in prostate cancer progression and may be a potential biomarker that will be useful for therapeutic targeting of prostate cancer." (PMID 31234468, 2019).
prostate carcinoma (continued). "We confirmed this speculation by showing that stable PXDN knockdown in C4-2 prostate cancer cells led to increased ROS levels, suggesting that PXDN is still acting as a ROS scavenger." (PMID 31234468, 2019). "Therefore, PXDN in prostate cancer cells may scavenge H2O2 to possibly prevent excessively high levels of ROS that may become deleterious for prostate cancer cells." (PMID 31234468, 2019). "Therefore, increased PXDN expression may be a potential biomarker for aggressive prostate cancer, and the inhibition of PXDN may be a possible therapeutic target for aggressive prostate cancer." (PMID 31234468, 2019). "In prostate cancer, PXDN promoter methylation has been shown to be mediated through PRMT5 leading to an increase in expression of PXDN." (PMID 37801286, 2023). "Therefore, PXDN expression may increase with prostate cancer progression." (PMID 31234468, 2019). "Therefore, we sought to investigate the role PXDN may play in prostate cancer." (PMID 31234468, 2019). "Therefore, the intriguing role PXDN may play in prostate cancer needs to be explored further." (PMID 31234468, 2019). "Notably, PXDN scavenges H2O2 in cardiovascular tissue, and it prevents oxidative stress in prostate cancer in vitro." (PMID 34439473, 2021). "We found increased expression of PXDN in prostate cancer tissue concurrent with tumor stage of prostate cancer patient tissue, while expression was undetectable/low in normal prostate epithelial tissue." (PMID 31234468, 2019). "There are few reports on PXDN in cancer and no current reports on the function of PXDN in prostate cancer." (PMID 31234468, 2019). "This revealed that the expression of PXDN was not detectable in normal tissue while it increased with the stage of prostate cancer." (PMID 31234468, 2019). "Peroxidasin (PXDN), a human homolog of Drosophila PXDN, belongs to the family of heme peroxidases and has been found to promote oxidative stress in cardiovascular tissue, however, its role in prostate cancer has not been previously elucidated." (PMID 31234468, 2019).
atherosclerosis (7 papers, 2013 to 2022). A disease characterized by the build-up of fatty material and calcium deposition in the arterial wall resulting in partial or complete occlusion of the arterial lumen. "Of relevance, aberrant PXDN expression has been associated with cardiovascular disorders, including endothelial dysfunction in hypertension, type 2 diabetes, and atherosclerosis." (PMID 35740014, 2022). "The role of peroxidasin in atherosclerosis is not fully understood and further studies are needed to determine if peroxidasin impacts the development of atherosclerosis." (PMID 35624738, 2022). "Among novel factors in atherosclerosis, we identified matrilin-2, the collagen IV crosslinking enzyme peroxidasin as well as the poorly characterized MAM-domain containing 2 (Mamdc2) protein as being up-regulated in the ECM during atherogenesis." (PMID 29208753, 2018).
lung carcinoma (5 papers, 2019 to 2023). "Analysis of transcriptomic data from larger lung cancer patient cohorts, however, revealed increased tumour expression of genes encoding both peroxidasin and ADAMTS16, and this was separately linked to poorer survival of lung adenocarcinoma and squamous cell carcinoma patients, respectively." (PMID 37397358, 2023). "Interestingly, the activity of peroxidasin is associated with accelerated tumorigenesis in murine models of lung carcinoma in the presence of inhalable fine particulate matter, which adsorbs peroxidasin and leads to accumulation of collagen cross-linking." (PMID 37397358, 2023).
pancreatic cancer (5 papers, 2022 to 2024). "In pancreatic cancer, high PXDN expression is associated with higher IC50 levels for drugs, indicating resistance." (PMID 39401197, 2024). "Complementing this, PXDN has also been predicted to be a target gene of miR-203 in pancreatic cancer." (PMID 37801286, 2023). "As some studies have found that the PXDN methylation level is significant in pancreatic cancer and colorectal tumors, we thus believe that the PXDN methylation level can be used as an independent predictor of tumor." (PMID 35982948, 2022).
colon cancer (4 papers, 2010 to 2019). "Knockdown of SLC25 in colon cancer cells suppressed proliferation, migration, and invasion in vitro and reduced the formation and metastasis of tumors in vivo, suggesting it is a metastasis promoter that can be suppressed by PXDN." (PMID 31234468, 2019).
microphthalmia (4 papers, 2014 to 2020). Congenital or developmental anomaly in which the eyeballs are abnormally small. "A Pxdn mutant mouse carrying a premature stop codon mutation was described to have a severe anterior segment dysgenesis and microphthalmia, resembling the phenotype in patients with PXDN mutations." (PMID 27409795, 2016). "Deficiency of peroxidasin in this mutant line results in anterior segment dysgenesis and microphthalmia." (PMID 24895407, 2014). "Besides anterior segment dysgenesis and microphthalmia, the main finding in this study is that peroxidasin has multiple roles during eye development influencing cell proliferation and differentiation and basement membrane consolidation." (PMID 24895407, 2014).
oral squamous cell carcinoma (4 papers, 2019 to 2023). "Furthermore, in oral squamous cell carcinoma, ROS production was found to have an inverse relationship with PXDN expression." (PMID 37801286, 2023).
type 2 diabetes (4 papers, 2022 to 2026). "Currently, PXDN is reported to play a critical role in tissue development and homeostasis and is involved in cardiovascular disease, type 2 diabetes, and hepatocyte fibrosis." (PMID 39399179, 2024). "PXDN, a 1,479-amino-acid secretory protein of the peroxidase XPO subfamily, is implicated in tissue development and homeostasis, with critical roles in cardiovascular disease, type 2 diabetes, and hepatocyte fibrosis." (PMID 41413560, 2025). "PXDN is also upregulated in aortas of rats with type 2 diabetes." (PMID 39399179, 2024).
congenital cataracts (3 papers, 2014 to 2020). "Recently, mutations in the human PXDN gene (OMIM 605158; encoding peroxidasin) were shown to cause a severe form of anterior segment dysgenesis, including corneal opacity, developmental glaucoma and congenital cataract." (PMID 24895407, 2014).
endothelial dysfunction (3 papers, 2020 to 2022). In vascular diseases, endothelial dysfunction is a systemic pathological state of the endothelium (the inner lining of blood vessels) and can be broadly defined as an imbalance between vasodilating and vasoconstricting substances produced by (or acting on) the endothelium. "The oxidation of uric acid by PXDN is likely a relevant mechanism in the endothelial dysfunction related to this metabolite." (PMID 35740014, 2022). "Apart from its role in the ECM network, over-expression of PXDN (also known as vascular peroxidase 1 or VSO1) during development of hypertension leads to endothelial dysfunction and attenuates NO production." (PMID 32094357, 2020).
gastric cancer (3 papers, 2022 to 2024). A primary or metastatic malignant neoplasm involving the stomach. "This may also be one of the potential mechanisms found in previous studies by which PXDN can act as an independent risk factor in gastric cancer." (PMID 35982948, 2022). "The GO term pathway analysis results show that ECM-associated pathways and their members, COL4A1, PXDN, and TGFBI, are involved in gastric cancer’s acquired drug resistance mechanism." (PMID 38968283, 2024). "We suggest that suppression and/or induction of COL4A1, PXDN and TGFBI and their molecular interplays enriched in the extracellular-related pathways may provide crucial clues to enhance gastric cancer’s chemosensitivity." (PMID 38968283, 2024). "Our results suggest that the suppression and/or induction of COL4A1, PXDN and TGFBI and their molecular interplays enriched in the Extracellular-related pathways may provide crucial clues to enhance the chemosensitivity of gastric cancer." (PMID 38968283, 2024). "We suggest that suppression and/or induction of COL4A1, PXDN, and TGFBI, and their molecular interplays involved in the ECM-related pathways may provide crucial clues to enhance the chemosensitivity of gastric cancer." (PMID 38968283, 2024). "Our GO term pathway analysis results strongly suggest that suppression and/or induction of COL4A1, PXDN and TGFBI and their molecular interplays involved in the extracellular-related pathways may provide crucial clues to enhance the chemosensitivity of gastric cancer." (PMID 38968283, 2024).
glioma (3 papers, 2019 to 2025). A benign or malignant brain and spinal cord tumor that arises from glial cells (astrocytes, oligodendrocytes, ependymal cells). "BMP2 and HEY2 were identified as protective factors (HR < 1), and NUP107, DRAM1, F2R, PXDN, RNF19A, and SCG5 were identified as risk factors for glioma (HR > 1)." (PMID 36245971, 2022). "In our study, the results of human tissue-based IHC staining and QRT-PCR experiments well confirmed the biological value of F2R, HEY2, PXDN, RNF19A, SCG5, and DRAM1 in glioma." (PMID 36245971, 2022).
lymph node metastasis (3 papers, 2020 to 2025). "High PXDN expression was significantly associated with the presence of lymph node metastasis (p = 0.0065)." (PMID 32751434, 2020). "Patients with high PXDN levels had worse disease free survival, lower levels of Reactive Oxygen Species (ROS), increased ATP production and increased lymph node metastasis." (PMID 37801286, 2023). "Significantly higher PXDN expression was observed in patients with lymph node metastasis (n = 22) than in those without (n = 24) (p = 0.0023)." (PMID 32751434, 2020).
Obesity (3 papers, 2021 to 2022). Accumulation of substantial excess body fat. "For example, peroxidasin homolog (PXDN) assists in extracellular matrix organisation and induces antimicrobial defence; however, the association between PXDN and diet-induced obesity remains unknown." (PMID 34066295, 2021).
abdominal aortic aneurysm (2 papers, 2022 to 2024). Enlargement and ballooning of the vessel that supplies arterial blood to the abdomen, pelvis and legs. "The obtained results suggested that AKG ameliorated abdominal aortic aneurysm via inhibiting PXDN/HOCL/ERK1/2 signaling pathways." (PMID 36209172, 2022). "However, peroxidasin/VPO1 is upregulated in vivo in inflamed or diseased cardiovascular tissue including human and mouse abdominal aortic aneurysms, atherosclerotic lesions in apoE−/− mice and in response to pathogenic stimuli, including angiotensin II." (PMID 39061857, 2024).
bladder cancer (2 papers, 2019 to 2022). "According to our results, PXDN tends to promote the development of prostate and bladder cancer, and this agrees with previous findings." (PMID 35982948, 2022).
brain tumor (2 papers, 2017 to 2019). "PXDN levels were found to be elevated in primary glial and secondary metastatic brain tumours as well as in its immediate microvasculature." (PMID 28378523, 2017).
colorectal cancer (2 papers, 2023 to 2025). A primary or metastatic malignant neoplasm that affects the colon or rectum. "We observed increased levels of numerous pro‐angiogenic proteins, including VEGF, PXDN, ANGPTL4 and TIMP‐1, a factor upregulated in colorectal cancer EVs that induces ECM remodelling in recipient fibroblasts." (PMID 41179923, 2025).
congenital glaucoma (2 papers, 2014 to 2016). "Therefore, peroxidasin could play a role in the onset of eye inflammation and congenital glaucoma." (PMID 24895407, 2014).
Corneal opacity (2 papers, 2014 to 2024). A reduction of corneal clarity. "Similarly, it is reported that mutations in the PXDN gene cause corneal opacity and CG and that mutations in the TEK gene likely underlie CG." (PMID 39158757, 2024).
head and neck carcinoma (2 papers, 2022 to 2025). A carcinoma that arises from the head and neck region. "The clinical relevance of PXDN was further substantiated across independent head and neck cancer cohorts, where its high expression consistently predicted poorer patient outcomes." (PMID 41413560, 2025).
Intellectual disability (2 papers, 2021 to 2024). "A deletion of a chromosome 2 region including the PXDN gene has also been associated with intellectual disability and obesity." (PMID 33414392, 2021).
Myocardial fibrosis (2 papers, 2022 to 2024). "It has been suggested that PXDN expression increases during myocardial ischemia-reperfusion injury and is involved in promoting myocardial fibrosis." (PMID 38517371, 2024).
myocardial infarction (2 papers, 2021 to 2022). Gross necrosis of the myocardium, as a result of interruption of the blood supply to the area, as in coronary thrombosis. "PXDN has been shown to be increased in the heart after cardiac stress or myocardial infarction after activation by elevated levels of TGF-β1." (PMID 33572894, 2021).
myocardial ischemia (2 papers, 2022 to 2024). A disorder of cardiac function caused by insufficient blood flow to the muscle tissue of the heart. "Previous studies have shown that PXDN promoted the cardiovascular oxidative damage, including cardiac fibrosis after MI, myocardial ischemia–reperfusion injury and hypertresion." (PMID 36209172, 2022).